AQP6 (aquaporin 6)
Description:
Aquaporins form homotetrameric transmembrane channels, with each monomer independently mediating water transport across the plasma membrane along its osmotic gradient. Unlike classical aquaporins, AQP6 is an intracellular channel with selective anion permeability, particularly for nitrate, and exhibits very low water permeability (By similarity). It may also facilitate the transport of gases, such as CO2 and NH4(+), as demonstrated in vitro (By similarity).
Synonyms: AQP2L; KID
Tractability: Antibody: UniProt predicts a signal peptide or a membrane-spanning region.
Gene: Protein-coding gene on chromosome 12 (49,967,194 to 49,977,139, forward strand). Ensembl gene ENSG00000086159.
Subcellular location: Cytoplasmic vesicle membrane
Pathways (Reactome):
Transport of small molecules: Passive transport by Aquaporins
Gene Ontology:
Molecular function: protein binding; water channel activity; ammonium channel activity; carbon dioxide transmembrane transporter activity; monoatomic anion channel activity; nitrate transmembrane transporter activity; pH-gated chloride channel activity; channel activity
Biological process: odontogenesis; renal water transport; carbon dioxide transport; nitrate transmembrane transport; ammonium transmembrane transport; carbon dioxide transmembrane transport; chloride transmembrane transport; monoatomic anion transmembrane transport; transmembrane transport
Cellular component: cytoplasmic vesicle membrane; membrane
Genetic constraint (gnomAD): Loss-of-function variants: 15 observed, 16.54 expected, observed/expected ratio (o/e) 0.91, 90% interval 0.61 to 1.4. The upper end of that interval is the gene's LOEUF score, 1.4, which puts it in group 5 of 6, group 1 being the genes least tolerant of losing a copy. Missense variants: 331 observed, 384.02 expected, observed/expected ratio (o/e) 0.86, 90% interval 0.79 to 0.94. Synonymous variants: 178 observed, 170.96 expected, observed/expected ratio (o/e) 1.04, 90% interval 0.92 to 1.18.
Homologues: Orthologues: chimpanzee AQP6 (99% identical), pig AQP6 (80% identical), macaque AQP6 (78% identical), rat Aqp6 (76% identical), guinea pig AQP6 (76% identical), mouse Aqp6 (75% identical), rabbit AQP6 (61% identical), dog AQP6 (35% identical), Drosophila melanogaster Drip (34% identical), Drosophila melanogaster Eglp2 (29% identical), Drosophila melanogaster Eglp4 (28% identical), Drosophila melanogaster Eglp3 (28% identical), and 7 more. Paralogues in human: AQP2 (55% identical), AQP5 (50% identical), MIP (47% identical), AQP1 (39% identical), AQP4 (39% identical), AQP7 (27% identical), AQP9 (27% identical), AQP7B (25% identical), AQP8 (25% identical), AQP3 (24% identical), AQP10 (21% identical).
Diseases named in the same sentence as AQP6 in open-access papers:
AQP6 is named in the same sentence as 28 diseases in open-access papers, as found by Europe PMC text mining. Sharing a sentence is not in itself a finding about the gene and the disease. The quoted sentences say what the papers report.
oncocytoma (3 papers, 2010 to 2022). "The reasons underlying the reduced expression of aquaporin 6 and increased expression of synaptogyrin-3 in chRCC, relative to oncocytoma are uncertain." (PMID 20462447, 2010). "Aquaporin 6 is an intracellular vesicle water channel protein reported to be expressed in the intercalated cells of the collecting duct, which is hypothesized to be the originating cell for oncocytoma and chRCC." (PMID 20462447, 2010). "For synaptogyrin-3, both N-18 and C-18 antibodies yielded a similar signal, but the N-18 antibody yielded a crisper result though the maximal signal was distinctly weaker compared to AQP6, for which crisp membranous staining was noted in oncocytoma, but not in chRCC." (PMID 20462447, 2010).
breast carcinoma (2 papers, 2022). "Of these AQPs, reduced expressions of AQP6 or AQP7 were associated with responders to aromatase inhibitors for Luminal A subtype breast cancer, whereas reduced AQP8 expression was associated with responders to anthracycline treatment for Luminal A subtype breast cancer." (PMID 36212456, 2022). "RT-qPCR of breast cancer and corresponding normal tissue did not detect the expression of AQP0, AQP2, and AQP6-9 mRNA." (PMID 36212456, 2022).
malignant pleural mesothelioma (2 papers, 2023 to 2024). A malignant neoplasm that arises from mesothelial cells in the pleura and shows a diffuse growth pattern. "In the hippocampus, AQP6, which has been characterised as a peroxiporin in malignant pleural mesothelioma, also was higher in the AD cohort." (PMID 36979749, 2023). "In malignant pleural mesothelioma cells confronted with heat stress, AQP6 silencing resulted in decreased H2O2 efflux and impaired cell proliferation, revealing AQP6 as an H2O2 channel and its protective feature towards ferroptosis." (PMID 39125952, 2024).
mesothelioma (2 papers, 2022 to 2024). A usually malignant and aggressive neoplasm of the mesothelium which is often associated with exposure to asbestos. "These experiments suggest that AQP6 is a crucial player in the etiology and also the resistance to chemotherapy in mesothelioma." (PMID 39125952, 2024). "Current findings suggest the major role of AQP-6 in providing mesothelioma cells with the ability to resist oxidative stress that underlies their resistance to chemotherapy drugs." (PMID 35741021, 2022). "Functional experiments performed in mesothelioma cells silenced for aquaporin-6 revealed that it is responsible, at least in part, for the increase in H2O2 efflux caused by heat stress." (PMID 35741021, 2022). "Recently, experimental data revealed the AQP6 peroxiporin activity in mesothelioma cells." (PMID 39125952, 2024). "Moreover, mesothelioma cells knocked down for AQP-6 showed a reduced proliferation compared to mock cells." (PMID 35741021, 2022).
ovarian carcinoma (2 papers, 2018 to 2020). A malignant neoplasm originating from the surface ovarian epithelium. "In this report, AQP6 mRNA expression found to be associated with better OS in all ovarian cancer patients, mainly in endometrioid cancer patients, as well as in all clinical stages and poorly differentiated ovarian cancer." (PMID 29472315, 2018). "Overexpression of AQP3, AQP6/2L, and AQP11 were associated with favorable OS in grade III ovarian cancer patients." (PMID 29472315, 2018). "AQP6 and AQP9 were reported to be downregulated, whereas AQP8 was unchanged, in ovarian cancer, but their roles remain to be determined." (PMID 32679804, 2020). "On the other hand, mRNA expression of AQP1 (grades I and II), AQP4 (grades I, II, and III), AQP6/2L (grade I), AQP10 (grade II) showed a worse OS in ovarian cancer patients." (PMID 29472315, 2018). "Our results revealed that higher AQP0, AQP1, and AQP4 mRNA expression were correlated with poor OS, whereas higher AQP3, AQP5, AQP6, AQP8, AQP10, and AQP11 showed better OS in ovarian cancer patients." (PMID 29472315, 2018). "Additionally, AQP3, AQP6, and AQP11 mRNA expression were correlated with better OS, whereas AQP0 and AQP1 showed poor OS in all ovarian cancer patients treated with Platin, Taxol, and Taxol + Platin chemotherapy." (PMID 29472315, 2018). "Intriguingly, when concurrent (Platin + Taxol) treatment and prognostic significance were analyzed, the data showed that high expression of AQP0 and AQP1 mRNA were correlated to decrease survival rate and high expression of AQP3, AQP6, and AQP11 were correlated to good OS in ovarian cancer patients." (PMID 29472315, 2018). "Nonetheless, whether or not AQP6 has a prognostic role in ovarian cancer remained elusive." (PMID 29472315, 2018). "Therefore, high AQP6 and AQP8 mRNA expression may predict a favorable prognosis in ovarian cancer." (PMID 29472315, 2018).
viral infections (2 papers, 2017 to 2018). "AQP6 expression in contrast might play a role in viral infections as it is decreased after viral infection and in turn can reduce the infectivity of Hazara virus." (PMID 29449936, 2018). "Furthermore, with Hazara virus as a model, we have recently provided an evidence for a protective role of AQP6 against virus infection." (PMID 29209610, 2017).
diabetes (1 paper, 2025). "At the FAIM2 locus on chr 12q13.12, we observed known genes associated with obesity, eating patterns, and diabetes-related traits, including ASIC1, AQP2, AQP5, AQP6, RACGAP1, and AC025154.2 (AQP5-AS1) along with FAIM2." (PMID 39813287, 2025).
gastric cancer (1 paper, 2018). A primary or metastatic malignant neoplasm involving the stomach. "The database results of individual AQPs correlation with different treatment strategy revealed that high expression of AQP0 and AQP6/2L were associated with poor OS in gastric cancer patients who received only surgery." (PMID 29678898, 2018). "In a recent preclinical study, AQP6 expression has been identified in rat gastrointestinal epithelium, however, the prognostic relation of AQP6 in human gastric cancer have rarely been reported in previous studies." (PMID 29678898, 2018). "AQP4 and AQP6/2L mRNA overexpression were correlated with poor OS in stage III gastric cancer." (PMID 29678898, 2018). "Nonetheless, AQP0, AQP6, and AQP8 mRNA expression with surgery alone and AQP9 mRNA with 5 FU chemotherapy were associated with significantly increased risk of low survival rate in gastric cancer patients." (PMID 29678898, 2018). "In which, we revealed AQP3, AQP9, and AQP11 mRNA expression were associated with improved OS in all gastric cancer patients especially with intestinal subtypes, whereas AQP0, AQP1, AQP4, AQP5, AQP6/2L AQP8, and AQP10 mRNA expression were associated with poor OS in all gastric cancer patients." (PMID 29678898, 2018). "Similarly, high expression of AQP3 and AQP9 mRNA revealed improved OS in female patients, whereas AQP0, AQP1, AQP6/2L and AQP8 were associated with poor OS in gastric cancer." (PMID 29678898, 2018). "In the present analysis, we revealed that AQP2, AQP6, AQP9, and AQP10 proteins were not expressed both in normal and gastric cancer tissues." (PMID 29678898, 2018).
kidney cancer (1 paper, 2022). Primary or metastatic malignant neoplasm involving the kidney. "The results showed that the expression levels of AQP0/1/2/3/4/5/7/8/11 in kidney cancer were significantly lower than those in normal tissues, while the expression level of AQP6 was up-regulated or down-regulated in different test results, which was inconsistent." (PMID 35245343, 2022).
ovarian tumor (1 paper, 2022). "Studies for the role of AQP6 in mammalian carcinogenesis have been largely lacking other than one report regarding AQP6 expression in ovarian tumor." (PMID 35847914, 2022).
periodontitis (1 paper, 2020). An acute or chronic inflammatory process that affects the tissues that surround and support the teeth. "We found an association between one marker (rs1996315) in AQP6 and periodontitis (p = 0.05)." (PMID 32130259, 2020). "Associations were found between the single nucleotide polymorphism (SNP) rs467323 in AQP2 and TMD in both genotypic (p = 0.03) and recessive (p = 0.02) models, and between rs1996315 in AQP6 and periodontitis (p = 0.05)." (PMID 32130259, 2020).
pleural mesothelioma (1 paper, 2022). A neoplasm that arises from the mesothelial cells of the pleura. "The involvement of aquaporin-6 in increasing the resistance to oxidative stress of malignant pleural mesothelioma cells undoubtedly provides new prominent information in understanding the role of peroxiporins in the redox regulation of malignant cells." (PMID 35741021, 2022).
tumor (8 papers, 2011 to 2026). "The increased expression of AQP6 in the membrane may be caused by the high oxidative state of the tumor cells, similar to what was previously demonstrated for AQP4 in astrocytes." (PMID 35741021, 2022). "Upregulated expression of AQP6 in ccRCC tumor tissues was observed in 2 datasets, while downregulated expression was observed in 6 datasets." (PMID 36254092, 2022). "By integrating these data, the expression of AQP5 and AQP6 was found to be significantly lower in tumor tissues but inapparent to clinical stage and pathological grade." (PMID 36254092, 2022). "In addition, AQP6 function was also examined because its significant upregulation in stromal tumor tissue was reported, but our results show a reduced expression in REN and MSTO-211H compared with MeT-5A." (PMID 35741021, 2022). "Only few studies have investigated AQP6 expression in tumor cells." (PMID 29678898, 2018). "We found that AQP1 (5.83e−07), AQP2 (0.0146), AQP4 (0.000382), AQP6 (0.0221), AQP7 (0.00052), AQP9 (8.2e−07) had significant correlations with the pathological stages of the tumor." (PMID 35245343, 2022). "According to the GEPIA database, AQP1, AQP3, AQP4, and AQP9 were significantly expressed in LUAD tissues compared to normal lung tissues (p < 0.05), but some genes including AQP0, AQP5, AQP6, AQP7, AQP8, AQP10, and AQP11 were not differentially expressed between tumor and normal tissues." (PMID 34708074, 2021).
cancer (2 papers, 2022 to 2026). A tumor composed of atypical neoplastic, often pleomorphic cells that invade other tissues. "Changes in aquaporin (AQP) expression, associated with CSCs and cancer cell migration, was assessed by immunodetection and RT‐qPCR, indicating a decrease in AQP3, AQP5 and AQP6 gene and protein expression upon DM treatment." (PMID 41318947, 2026). "Since peroxiporin-mediated H2O2 signaling has been demonstrated to be involved in cancer progression, proliferation, and metastasis, in this study, we evaluated the effect of AQP6 silencing in the proliferation of MPM cells." (PMID 35741021, 2022). "The localization in the plasma membrane of an AQP typically located in intracellular structures may suggest the involvement of AQP6 in cancer growth and progression." (PMID 35741021, 2022). "AQP6 reduction by esiRNA treatment was found to suppress MPM cancer proliferation by about 50%." (PMID 35741021, 2022).
infection (2 papers, 2017 to 2022). The state of being infected such as from the introduction of a foreign agent such as serum, vaccine, antigenic substance or organism. "The transcriptome of the tubular epithelial- and podocyte-specific genes, AQP1, AQP6, NPHS2, SCL12A1, was examined over a period of 11 days for toxic and ischemic and of up to 24 days for nephritic and infection-associated AKI." (PMID 36285332, 2022). "Using confocal imaging and immunoblotting, we observed that the F-actin was disrupted and the expression and distribution of IQGAP1 and AQP6 were reduced upon Hazara infection." (PMID 29209610, 2017). "An infection of human cells with CCHFV strain IbAR 10200 downregulated the AQP6 mRNA expression." (PMID 29209610, 2017).
AQP6 also shares sentences with these, for which no sentence is quoted: clear cell renal cell carcinoma (1 paper); cognitive decline (1); dementia (1); endometrioid ovarian cancer (1); kidney disease (1); lung adenocarcinoma (1); Obesity (1); papillary renal cell carcinoma (1); renal cell carcinoma (1); Renal oncocytoma (1); renal pelvis urothelial carcinoma (1); renal Wilms tumor (1); serous ovarian cancer (1).